MIR1307 (microRNA 1307)
Synonyms: hsa-mir-1307; MIRN1307; mir-1307
Gene: MicroRNA gene on chromosome 10 (103,394,253 to 103,394,401, reverse strand). Ensembl gene ENSG00000283867.
Gene Ontology:
Biological process: miRNA-mediated post-transcriptional gene silencing
Cellular component: RISC complex
Homologues: Orthologues: chimpanzee ptr-mir-1307 (100% identical), macaque MIR1307 (100% identical), pig ssc-mir-1307 (53% identical), rabbit ocu-mir-1307 (42% identical).
Diseases named in the same sentence as MIR1307 in open-access papers:
MIR1307 is named in the same sentence as 3 diseases in open-access papers, as found by Europe PMC text mining. Sharing a sentence is not in itself a finding about the gene and the disease. The quoted sentences say what the papers report.
chronic pancreatitis (1 paper, 2021). A chronic inflammatory process causing damage and fibrosis of the pancreatic parenchyma. "MIR1307 was strongly expressed in the tumour component of PDAC tissues when assessed by in situ hybridization, while areas with chronic pancreatitis adjacent to the tumour were at most weakly positive." (PMID 34795259, 2021).
pancreatic cancer (1 paper, 2021). "Here, the authors show that the MIR1307 is increased in a subgroup of human pancreatic cancers and inhibition of the microRNA in in vitro and in vivo models of pancreatic cancer sensitises cells to treatment." (PMID 34795259, 2021).
tumour (1 paper, 2021). "In line with our in vitro data, MIR1307 disruption makes tumours more prone to undergo DNA damage in vivo as highlighted by the high pH2Ax and caspase 3 in FOI-treated MIR1307KO xenografts compared to WT." (PMID 34795259, 2021). "Although we cannot exclude an effect of MIR1307 on tumour growth, our data support an effect of MIR1307 on FOI resistance." (PMID 34795259, 2021). "Conversely to MIR374A*, MIR1307 was expressed in human pancreatic tissues and was increased in the tumour in comparison to the matched adjacent counterpart." (PMID 34795259, 2021). "In an extended cohort of 59 cases, MIR1307 was increased by >1.3 fold in tumour vs adjacent tissue in 29 cases." (PMID 34795259, 2021).